BRCA1 (BRCA1 DNA repair associated)
Diseases named in the same sentence as BRCA1 in open-access papers (continued):
Sharing a sentence is not in itself a finding about the gene and the disease.
cancer (continued). "Mutations in DNA repair genes, including breast cancer susceptibility 1 (BRCA1), are closely linked to the development of cancer." (PMID 21666281, 2011). "We investigated the prevalence of the BRCA1 founder mutations c.4034delA and c.5266dupC in a population-based series of unselected breast (n = 2546) and ovarian (n = 795) cancer cases." (PMID 22032251, 2011). "BRCA-deficiency in cancer cell can be caused either by germ-line mutation followed by the "second hit", or by somatic inactivation of the BRCA1 gene." (PMID 21819606, 2011). "More than 1000 distinct cancer-associated BRCA1 [MIM 113705] mutations have been already described; however, not all of them are equally pathogenic and most probably there is a different cancer risk associated with specific mutations." (PMID 22032251, 2011). "Studies of Utah high-risk pedigrees identified in the UPDB have lead to the discovery of multiple cancer predisposition genes including BRCA1, BRCA2, p16, and HPC2/ELAC2." (PMID 21619629, 2011). "Most cancer-causing mutations within the BRCA1 gene have been found in the N- and C-terminal regions of the protein." (PMID 21666281, 2011). "An emerging concept in cancer therapeutics is the synthetic lethality-based treatment of tumors harboring BRCA1/2 mutations with poly(ADP-ribose) polymerase (PARP) inhibitors." (PMID 21998700, 2011). "Further studies are warranted to evaluate if metformin treatment significantly modifies cancer risk due to deleterious BRCA1 gene mutations to decrease middle-age women mortality and/or late-onset familial cancer." (PMID 21483040, 2011). "Hereditary cancer institute database contains information about 207 families of BRCA1 founder mutation carriers (including 79 families of c.4034delA and 128 families of c.5266dupC mutation carriers) who were identified during genetic screening in Latvia." (PMID 22032251, 2011). "Among sporadic cancers, basal-like tumors are showing most genetic and phenotypic similarities to the aggressive tumors arising in BRCA1 germ line mutation carriers." (PMID 21276239, 2011). "This triple-negative status renders BRCA1-associated cancers insensitive to hormonal manipulation or targeted therapy with trastuzumab, respectively." (PMID 21771338, 2011). "Subsequent phase I clinical trials have established the safety of single-agent PARPi in the advanced cancer population as well as in BRCA1/2 mutation carriers." (PMID 21989215, 2011). "Some BRCA1-related cancers appear to be caused by gene conversion events in individuals carrying one mutant BRCA1 allele." (PMID 21291537, 2011). "Nine percent of these cancers show alterations in BRCA1 gene while 3 percent have shown BRCA2 variants." (PMID 21559243, 2011). "Such evidence suggests that genetic or other risk factors that cluster in families modify the cancer risks conferred by BRCA1 and BRCA2 mutations." (PMID 22053997, 2011). "It has been known for some time that there are particular morphological and histopathological features evident on tumour review that are more common in cancers arising in BRCA1 mutation carriers." (PMID 21343941, 2011). "Allelic expression imbalance has also been studied in the cancer associated genes BRCA1/2 and CDH1 and used to identify polymorphisms, mutations and other defects that alter allelic expression and influence disease state." (PMID 21345208, 2011). "Mice deficient for Mdc1, Rnf8, 53bp1 or Brca1 have increased cancer susceptibility likely due to their elevated levels of genomic instability." (PMID 21552324, 2011). "Consistently, 3q gains are most frequently observed in tumors arising in BRCA1 mutation carriers and, among sporadic cancers, seen with highest incidence in basal-like tumors (20% of cases, in comparison to 10% of luminal tumors)." (PMID 21276239, 2011). "Several studies of Rad51 among BRCA1 mutation carriers have found positive associations with cancer risk." (PMID 21708019, 2011).
cancer (continued). "Combined with our data, it appears that loss of BRCA1 or BRCA2 function results in a more proliferative luminal cancer when an ER+ cancer develops." (PMID 21080930, 2010). "Over the past ten years, the focus of management for those identified as BRCA1/2 mutation carriers has been on cancer prevention and early cancer detection." (PMID 20049345, 2010). "In the 77 BRCA1 cancers we studied, only one BRCA1-associated cancer with loss of wt BRCA1 demonstrated HER2 gene amplification by FISH." (PMID 21080930, 2010). "Loss of wt BRCA1 was equally frequent in ER+ and ER- BRCA1-associated cancers (81.0% vs 88.6%, respectively; P = 0.53)." (PMID 21080930, 2010). "Our current findings that ER+ cancers with loss of wt BRCA1 are significantly more often higher grade cancers is a consistent extension of our original results." (PMID 21080930, 2010). "The prevalence of loss of wt BRCA1 in these ER+ tumors was similar to that seen in the ER- BRCA1-associated cancers (88.6%)." (PMID 21080930, 2010). "We estimated risks of breast and other cancers for groups of relatives defined by the BRCA1 and/or BRCA2 mutation status of their index case." (PMID 20877337, 2010). "Only two of these prior studies included any ER+ BRCA1 cancers and reported loss of wt BRCA1 in 75% and 83% of such cancers." (PMID 21080930, 2010). "Cancers with loss of wt BRCA1 were more likely to express either CK5/6 or CK14 even after Bonferroni adjustment for multiple comparisons and in multinomial logistic regression (odds ratio (OR), 4.7; 95% CI, 1.85 to ∞)." (PMID 21080930, 2010). "ER+ BRCA1 cancers were less likely than ER- BRCA1 cancers to have "BRCA-associated" features such as high mitotic activity, geographic necrosis/fibrotic focus, and pushing margins (RR 0.06, 0.22, 0.24; P < 0.001, 0.02, 0.03 respectively)." (PMID 20149218, 2010). "In the BRCA1-associated cancers in this study, LOH with loss of either the wt or mutant BRCA1 allele was observed in 97% of ER- and 90% of ER+ cases." (PMID 21080930, 2010). "Our results regarding HER2 overexpression/gene amplification in BRCA1-associated cancers are consistent with prior studies that have found that HER2 overexpression and amplification are uncommon in these tumors." (PMID 21080930, 2010). "When compared to sporadic ER+ cancers, ER+ BRCA1-associated cancers are more often of invasive ductal type and exhibit a high mitotic rate." (PMID 21080930, 2010). "While the spectrum of BRCA1 mutations was varied in this group of 77 cancers, 57% of the mutations were Ashkenazi mutations reflecting the significant Jewish population in the communities served by the participating hospitals." (PMID 21080930, 2010). "One way to address this issue is to analyze ER+ cancers that arise in BRCA1 mutation carriers for loss of the wild type (wt) BRCA1 allele." (PMID 21080930, 2010). "Previously, we have described that ER+ BRCA1-associated cancers are more often high grade ductal cancers compared to age matched ER+ sporadic breast cancers." (PMID 21080930, 2010). "Cancers with loss of wt BRCA1 were also more likely to exhibit expression for CK5/6 (P < 0.001), CK14 (P = 0.023) or either CK5/6 or CK14 (P < 0.001)." (PMID 21080930, 2010). "Previous publications indicate that a BRCA1 mutation is associated with cancer progression through pathways of cell proliferation, differentiation, and apoptosis." (PMID 20576130, 2010). "BRCA1 cancers with loss of wt BRCA1 were more likely to express basal cytokeratins CK 5/6 or 14 (OR 4.7; 95% CI, 1.85 to ∞)." (PMID 21080930, 2010). "Mutations in the RING finger domain of BRCA1 are thought to predispose to the development of cancer because they abrogate ubiquitin ligase activity." (PMID 20182637, 2010). "It has also been shown that BRCA1-dependent ubiquitination is important in regulating centrosome number, and centrosome amplification is a hallmark of cancer." (PMID 21103054, 2010).
cancer (continued). "In contrast, 11 of 33 ER+ cancers with loss of wt BRCA1 (33.3%) showed expression for one or the other of these basal cytokeratins." (PMID 21080930, 2010). "Six cancers (three ER+ and three ER-) with insertion/deletion mutations had m% < 40% and one cancer (ER+) with a point mutation had an NM score > 1.4 consistent with LOH with loss of the mutant BRCA1 allele." (PMID 21080930, 2010). "BRCA1 promoter methylation is a potential alternative mechanism to LOH for providing the "second hit" to inactivate wt BRCA1 in BRCA1-associated cancers." (PMID 21080930, 2010). "The distributions for m% and NM_score for ER+ and ER- BRCA1-associated cancers were roughly similar." (PMID 21080930, 2010). "A recent population-based study from Canada suggested that BRCA1/2 mutations were associated with a significantly increased risk of cancers overall and at sites other than breast and ovary." (PMID 19277124, 2009). "This is in agreement with data showing that mutations in the BRCA1 gene are rarely linked to cancer at sites other than breast and ovary, while mutations in the BRCA2 gene are." (PMID 19329713, 2009). "This suggested to us that either the 185delAG mutation is of low penetrance or, more likely, carriers of this mutation would develop cancer at an older age compared with other BRCA1 gene mutations." (PMID 19329713, 2009). "VHL and BRCA1 are also frequently mutated in cancer, but for other tumour suppressor genes, such as RASSF1A, promoter hypermethylation appears to be the principal mechanism for inactivation." (PMID 19285540, 2009). "BRCA1-associated cancers are typically high-grade and are 'triple negative'; i.e. are negative for estrogen-receptor (ER), progesterone-receptor (PR) and HER2 expression." (PMID 19298662, 2009). "An overall test of association for men and women together showed a statistically significant association between BRCA1/2 mutations and increased non-cancer mortality (p = 0.024)." (PMID 19277124, 2009). "We were able to use a kin-cohort analysis that accounts for informative censoring to estimate the effect of BRCA1/2 mutations on mortality with the effect of mortality directly related to cancer removed." (PMID 19277124, 2009). "In this study, we observed an overall association between BRCA1/2 mutations and reduced life expectancy after excluding deaths following diagnosis of the cancers that have been shown to be related to these mutations." (PMID 19277124, 2009). "The aim of this study was to elaborate on the expressivity of various BRCA1 gene mutations in relation to penetrance and age of cancer diagnosis." (PMID 19329713, 2009). "We then asked if the relationship between various BRCA1 exon mutations and age at diagnosis is different for different cancer sites." (PMID 19329713, 2009). "In conclusion, we observed an excess in non-cancer mortality associated with the founder BRCA1/2 mutations among an Ashkenazi Jewish cohort, with a reduction in life expectancy of approximately 4–6 years." (PMID 19277124, 2009). "Nevertheless, assessment of the likelihood of carrying deleterious mutations in BRCA1 or BRCA2 genes among patients who present high-risk cancer evaluation clinics will provide more accurate guidance to women and families about considering genetic testing." (PMID 19619314, 2009). "BRCA1 is a tumor suppressor gene whose altered function is associated with breast, ovarian and other cancers." (PMID 19695104, 2009). "Here we describe the interactions we found out in this group between MDM2 SNP309 G/G, BRCA1/2 mutations and clinical findings including cancer onset age, survival, and the presence of other cancers." (PMID 19226467, 2009). "More than 2,600 cancer predisposing mutations have been identified in BRCA1 and BRCA2 genes, on chromosome 17 and 13 respectively." (PMID 19825178, 2009). "The question of why the 185delAG mutation has a lower cancer-related expressivity that is age dependent compared to other BRCA1 mutations remains to be elucidated." (PMID 19329713, 2009).
cancer (continued). "We and others have recently shown that carcinomas from patients with inherited frameshift mutations in BRCA1 or BRCA2 exposed to chemotherapy can acquire secondary mutations that restore the reading frame of BRCA1 or BRCA2, resulting in platinum resistance." (PMID 19602291, 2009). "Thrall and colleagues evaluated a large number of sporadic advanced stage carcinomas and found that BRCA1 loss was strongly protective for overall survival." (PMID 19602291, 2009). "The finding that BRCA1 is a corepressor of ERα provides a potential molecular explanation for the tissue-specific nature of BRCA1-associated cancer." (PMID 18847501, 2008). "We recently confirmed that cells expressing these markers define a cancer stem cell in Brca1 deficient cell lines." (PMID 18394172, 2008). "The variability of cancer risk among BRCA1/2 carriers suggests a role for environmental and genetic modifiers." (PMID 18542066, 2008). "A BRCA1/2 mutation screen was performed on 145 families and a cancer predisposing mutation was found in 56 (39%)." (PMID 18783588, 2008). "We consider that widespread somatic methylation of BRCA1 is an important and as yet unrecognised cause of some BRCA1-like cancers." (PMID 18269736, 2008). "The cancer risks among BRCA1 and BRCA2 mutation carriers, and the polygenic variance, were assumed to be the same in the Ashkenazi and non-Ashkenazi versions." (PMID 18349832, 2008). "These criteria have been derived from estimates based on data from cancer-prone families or from BRCA1/2 mutation families." (PMID 18651949, 2008). "In the study conducted by Foulkes and colleagues, CK-5/6 was detected in 56% of the 72 ER/HER2-negative cancers, and the frequency was even higher (88%) among the 17 BRCA1 mutation carriers with ER/HER2-negative cancers." (PMID 18275599, 2008). "A practical implication is that only 4 PCR fragments can be used in a first screen and reveal the cancer predisposing mutation in 67% of the BRCA1/2 positive families." (PMID 18783588, 2008). "In the context of high risk families studies have provided the evidence for at least two major cancer susceptibility genes: BRCA1 (17q21) and BRCA2 (13q12)." (PMID 18783588, 2008). "The presence of recurrent mutations in this population permits the identification of cancer predisposing mutations in 67% of the BRCA1/2 mutant families by just analyzing 4 PCR fragments by DGGE." (PMID 18783588, 2008). "Rachel Klevit's group determined that several of the cancer-predisposing mutations in BRCA1 result in defective E3 activity in vitro by disrupting BRCA1/BARD1 heterodimer formation or by altering the RING domain structure of BRCA1." (PMID 19007437, 2008). "There is no reason to believe that carriers of BRCA2 mutations should have greater mortality than men with BRCA1 mutations from non-cancer causes, and men with other forms of cancer were excluded." (PMID 18577985, 2008). "The aim of our study was to assess: (i) the nature of BRCA1/2 mutations found in Slovenian population and (ii) the cancer phenotype in BRCA1/2 mutation positive families." (PMID 18783588, 2008). "A higher rate of "medullary like" carcinoma is typical of BRCA1 mutation carriers and this diagnosis is associated with a relatively good prognosis." (PMID 18405391, 2008). "The basal-like subtype has been shown to have the highest proliferation rates and poorest outcomes, and has been described in association with BRCA-1-associated carcinomas." (PMID 18179684, 2008). "Other tumor types were much less frequent, although it is noteworthy that all 5 patients with "medullary like" carcinoma came from the BRCA1 mutation carriers group (10%)." (PMID 18405391, 2008).
cancer (continued). "For this, we integrate estimates of the risk of developing a cancer for BRCA1-carriers into population genetics frameworks, and calculate selection coefficients on BRCA1 alleles for different demographic scenarios varying across the extent of human demography." (PMID 18030340, 2007). "Cancer-associated mutations in BRCA1 can prevent nuclear localisation of BRCA1 and its contribution to nuclear DNA repair foci formation in response to DNA damage (for example, by ionising radiation [IR])." (PMID 18036263, 2007). "The increased chance of developing BC and PC in individuals with either the BRCA1 or BRCA2 mutation is consistent with the increased bcl-2 caused by the elimination of PRB being partly responsible for the increased incidence of cancer." (PMID 17678531, 2007). "BRCA1 is involved in the regulation of centrosomes, and some cancer-associated mutations are associated with centrosome amplification." (PMID 18036263, 2007). "Our results are based on an estimation of the cumulative risk of developing cancers, averaged over all BRCA1 mutations, and we therefore cannot differentiate the magnitude of selection acting on different alleles." (PMID 18030340, 2007). "It will therefore be extremely interesting in the future to compare the aCGH profiles of our MBCs with those of BRCA1-associated carcinomas." (PMID 17417968, 2007). "BRCA1 germ-line mutations are also associated with an increased risk of other cancer types, including those affecting colon, pancreas, stomach and fallopian tubes." (PMID 16764716, 2006). "It has been shown that gross chromosomal changes are more likely to occur in cancers occurring in individuals with germline mutations in BRCA1 and BRCA2 compared with sporadic cancers." (PMID 16404418, 2006). "Other possible sites of cancer for BRCA1 mutation carriers included cutaneous melanoma, basal cell carcinoma and sarcoma." (PMID 16764716, 2006). "This study shows that CPM significantly reduces the risk for contralateral cancer among BRCA1 or BRCA2 mutation carriers." (PMID 16052221, 2005). "Subgroup analyses according to BRCA mutation status showed that among women with a BRCA1 mutation, weight loss of at least 10 pounds was associated with a 65% reduction in cancer risk compared with women in the reference group (OR = 0.35)." (PMID 16168130, 2005). "In a logistic regression analysis comparing BRCA2-associated cancers with non-BRCA1/2 cancers and taking into account age, grade and all tested histological and immunohistochemical factors, the only independently significant factor was age (P = 0.0001)." (PMID 15642173, 2005). "Eleven of the 178 X chromosome mapped transcripts were differentially expressed between the BRCA1-associated and sporadic cancers (P < 0.005)." (PMID 15383145, 2004). "Forty of 178 total X-chromosome transcripts were differentially expressed between the BRCA1-associated tumors and sporadic cancers with a BRCA2-like molecular profile." (PMID 15383145, 2004). "We screened the complete coding region of both genes in 451 individuals from 349 Belgian families referred to a family cancer clinic and identified 49 families with a BRCA1 and 26 families with a BRCA2 mutation." (PMID 15026808, 2004). "Firstly, despite varying the penetrance estimates (the likelihood of developing cancer), they have confined their analysis to BRCA1/2 mutation carriers only." (PMID 15138471, 2004). "Cost per BRCA1 mutation detected among members of high-risk families with a living cancer-affected relative or stored sample of their blood/DNA has been estimated to range between £74 [£90] and €6881.70 (£4328)." (PMID 15150621, 2004). "One of the unexplained features of germ-line BRCA1 mutations is the overwhelmingly disproportionate risk of cancer in female carriers." (PMID 15383145, 2004).